SNORD57 (small nucleolar RNA, C/D box 57)
Synonyms: U57; RNU57
Gene: Small nucleolar RNA gene on chromosome 20 (2,656,939 to 2,657,010, forward strand). Ensembl gene ENSG00000226572.
Gene Ontology:
Biological process: RNA processing
Cellular component: nucleolus
Homologues: Orthologues: macaque SNORD57 (97% identical), pig SNORD57 (96% identical), rabbit SNORD57 (86% identical), rat Snord57 (86% identical), mouse Snord57 (81% identical), tropical clawed frog SNORD57 (76% identical).
Diseases named in the same sentence as SNORD57 in open-access papers:
SNORD57 is named in the same sentence as 2 diseases in open-access papers, as found by Europe PMC text mining. Sharing a sentence is not in itself a finding about the gene and the disease.
SNORD57 shares sentences with these, for which no sentence is quoted: glial tumors (1 paper); tumor (1).